MAPK11 (mitogen-activated protein kinase 11)
Diseases named in the same sentence as MAPK11 in open-access papers:
MAPK11 is named in the same sentence as 90 diseases in open-access papers, as found by Europe PMC text mining. Sharing a sentence is not in itself a finding about the gene and the disease. The quoted sentences say what the papers report.
breast carcinoma (13 papers, 2013 to 2025). "MAPK11 plays a role in a variety of female tumors (breast cancer, uterine endometrial cancer, cervical cancer, ovarian cancer, and uterine carcinosarcoma), and its expression levels are significantly reduced." (PMID 38495669, 2024). "Moreover, it was found that MAPK11 (p38β) activation in breast cancer cells has given rise to elevated CCL2 production, which then contributed to increased bone resorption." (PMID 32582148, 2020). "Strikingly, MAP3K1, MAPK11, PPP2R1A, and α2 integrin expression were higher in chemotherapy-resistant tumours in breast cancer patients." (PMID 39666682, 2024). "Consistently, we showed that MAP3K1, MAPK11, PPP2R1A, and α2 integrin expression is higher in chemoresistant breast cancer patients." (PMID 39666682, 2024). "Furthermore, there was a similar observation with our finding that mitogen-activated protein kinase 11 (MAPK11) was highly expressed in metastatic breast cancer patients and in the breast cancer cell lines." (PMID 34540825, 2021). "To examine whether regulators of ECM internalisation may impact on chemoresistance in breast cancer patients, we looked at the correlation between MAP3K1, MAPK11, PPP2R1A, and α2 integrin expression and chemotherapy response using transcriptomic data of 3,104 breast cancer patients." (PMID 39666682, 2024). "For example, primary tumors of breast cancer, lung adenocarcinoma, and glioblastoma multiforme have similar or significantly lower MAPK11 (p38β) and MAPK12 (p38γ) protein expression levels compared to normal tissue." (PMID 35501462, 2022).
cardiac hypertrophy (6 papers, 2012 to 2022). "Mapk11 encoded p38 mitogen-activated protein kinase paly pivotal pathophysiological role in diabetic cardiomyopathy, cardiac ischemia/reperfusion injury, and cardiac hypertrophy." (PMID 36733828, 2022).
hepatocellular carcinoma (6 papers, 2019 to 2025). A malignant tumor that arises from hepatocytes. "Circ 0001955, TRAF6, and MAPK11 are upregulated in hepatocellular carcinoma, whereas miR 145 5p and miR 516a 5p are downregulated." (PMID 41465470, 2025). "It has been reported that MAPK10 can regulate the inflammatory response in human osteoarthritis and astrocytes, and MAPK11 can regulate the inflammatory response in human hepatoma cells and mice." (PMID 37570275, 2023). "Furthermore, MAPK11 plays a key role in the invasion and migration of cancer cells in breast, endometrial, and hepatocellular carcinomas." (PMID 38727302, 2024). "Collectively, these mechanisms allow circ0001955 to restore the carcinogenic activity of ARF6, SPATS2, TRAF6, and MAPK11 in chronically HCV-infected hepatocytes, promoting the initiation and progression of hepatocellular carcinoma." (PMID 41465470, 2025).
colorectal cancer (5 papers, 2013 to 2024). A primary or metastatic malignant neoplasm that affects the colon or rectum. "Mapk11 has been reported as a cell proliferation-promoting oncogene upregulated in hepatocarcinoma (HCC) and colorectal cancer (CRC), among others." (PMID 39125691, 2024).
melanoma (4 papers, 2015 to 2024). A malignant, usually aggressive tumor composed of atypical, neoplastic melanocytes. "When comparing the difference in the DEGs by recurrence status in both age groups, we found that MAPK11 was highly expressed in the younger melanoma patients in the recuryes versus the recurno group (FC=2.84)." (PMID 33373316, 2020). "Indeed, MAPK14 is up-regulated in BRAF-inhibition-resistant melanoma in mouse models, while MAPK11 abrogation promotes radiosensitivity in A549, MCF7, and HCT-116 cells." (PMID 39666682, 2024). "On the other hand, the top downregulated genes formed 4 subgroups and were related to melanogenesis (Wnt5a, Mitf, Pomc, Mc1r, Kit), melanoma (Fgf9, Fgf12, Fgf2), MAPK signaling pathway (Ncam1, Prkcb, Map3k4, Pla2g4a, Mapk14, Mapk11), and aging (Tgfbr1, Il6, Nox4)." (PMID 36555664, 2022).
COVID-19 (3 papers, 2023 to 2025). A disease caused by infection with severe acute respiratory syndrome coronavirus 2. "MAPK11 is targeted by the compound losmapimod, which was tested against COVID-19 in a (terminated) phase III clinical trial (NCT04511819)." (PMID 37137934, 2023).
endometrial carcinoma (3 papers, 2019 to 2025). A malignant tumor arising from the epithelium that lines the cavity of the uterine body. "More importantly, MAPK11 can reverse the effect of LINC01220 on endometrial cancer cells." (PMID 31123170, 2019). "MAPK11, as one of the subunits of MAPK, its overexpression enhances the proliferation and colony formation ability of endometrial carcinoma cells." (PMID 40996975, 2025).
viral infection (3 papers, 2018 to 2024). "The qRT-PCR results indicated an up-regulation trend for DDX58, STAT1, and MX1, while IRAK1, MAPK11, RELA, and ICAM1 exhibited a down-regulation trend as the duration of the viral infection increased." (PMID 38673764, 2024). "We first screened the four p38 isoforms (p38ɑ/MAPK14, p38β/MAPK11, p38γ/MAPK12, and p38δ/MAPK13) as functional differences between the isoforms in the context of virus infection are particularly understudied." (PMID 37345956, 2023).
amyotrophic lateral sclerosis (2 papers, 2014 to 2024). Amyotrophic lateral sclerosis (ALS) is a neurodegenerative disease characterized by progressive muscular paralysis reflecting degeneration of motor neurons in the primary motor cortex, corticospinal tracts, brainstem and spinal cord. "The inhibition of MAPK11-involved astrocyte inflammation and the enhancement of antioxidant capacity are essential mechanisms by which MSC-Exos improve the prognosis of amyotrophic lateral sclerosis (ALS)." (PMID 38372822, 2024).
brucellosis (2 papers, 2025). Brucellosis is a bacterial infection that spreads from animals to people via unpasteurized dairy products or by exposure to contaminated animal products or infected animals. "The abnormal levels of CDK1, MAPK11, PDIA3, and immune cells in brucellosis may be involved in the disease’s pathogenic mechanisms." (PMID 40996975, 2025). "Importantly, through the analysis with GBM and Random Forest models, CDK1, MAPK11, and PDIA3 were further identified as potential diagnostic marker genes for brucellosis." (PMID 40996975, 2025). "In the GSE69597 dataset, the expression levels of CDK1, MAPK11, and PDIA3 were significantly higher in patients with brucellosis compared to the control group." (PMID 40996975, 2025). "RT-qPCR validation confirmed that the mRNA levels of CDK1, MAPK11, and PDIA3 were significantly elevated in brucellosis patients compared to the control group." (PMID 40996975, 2025). "Similarly, Western blot experiments revealed that the protein expression levels of CDK1, MAPK11, and PDIA3 were significantly higher in patients with brucellosis than in the control group." (PMID 40996975, 2025).
glioblastoma (2 papers, 2022 to 2024). The most malignant astrocytic tumor (WHO grade IV). "Dual inhibition of MAPK11 and MAPK14 is currently being tested as a monotherapy or in combination with other agents, such as gemcitabine and carboplatin, for the treatment of glioblastoma, ovarian, and metastatic breast cancer." (PMID 39666682, 2024).
kidney carcinoma (2 papers, 2013 to 2024). Primary or metastatic malignant neoplasm involving the kidney. "Similarly, both Mapk11 and Il6 are cancer-related FDA-approved drug targets and correspond to markers for an unfavorable prognosis for renal cancer." (PMID 39125691, 2024).
prostate carcinoma (2 papers, 2016 to 2023). A carcinoma that arises from epithelial cells of the prostate gland. "In osteolytic prostate cancer cells, MAPK11 correlates with Dickkopf-1 expression in different stages of prostate cancer and is associated with prostate cancer metastasis." (PMID 37394064, 2023). "In summary, the p38 MAPK isoform, MAPK11 correlates with DKK-1 expression in different stages of prostate cancer and is the main p38 MAPK isoform regulating DKK-1 expression in osteolytic prostate cancer cells in vitro." (PMID 26913608, 2016).
depression (1 paper, 2015). "It was found that highly variable probes in depression-discordant MZ pairs were located in genes within enriched biological pathways and previously associated with depression, such as CACNA1C, IGF2 and MAPK11." (PMID 25918994, 2015).
endothelial dysfunction (1 paper, 2022). In vascular diseases, endothelial dysfunction is a systemic pathological state of the endothelium (the inner lining of blood vessels) and can be broadly defined as an imbalance between vasodilating and vasoconstricting substances produced by (or acting on) the endothelium. "Acute H O activation of MAPK11-p38 is the main cause of endothelial dysfunction during pregnancy." (PMID 36338963, 2022).
glioma (1 paper, 2023). A benign or malignant brain and spinal cord tumor that arises from glial cells (astrocytes, oligodendrocytes, ependymal cells). "ESR11, MAPK11, and HSP90AB11, may be the key targets of the treatment for glioma." (PMID 38003496, 2023).
herpes simplex infection (1 paper, 2019). "For the thymus, the NOD-like receptor signaling pathway (PLCB1/MAPK11), the MAPK signaling pathway (SRF/MAPK11), influenza A (RSAD2/MAPK11), and MAPK11 (salmonella, toll-like, herpes simplex infection) were observed." (PMID 30769908, 2019).
leishmaniasis (1 paper, 2025). Infectious disease that is transmitted through the bite of hematophagous female phlebotomine sand flies. "Analysis of overlapping downregulated DEGs in the leishmaniasis and toxoplasmosis pathways identified key association with Tnf, Mapk11, Tbfb3, Stat1, and MHC Class II-related genes (H2-Oa, H2-DMb1, H2-Aa, H2-Dma, H2-Eb1, and H2-Ab1)." (PMID 40206211, 2025).
oral lichen planus (1 paper, 2025). Oral lichen planus is a chronic inflammatory oral condition of unknown aetiology characterized by T-cell-mediated chronic immune response and abnormal epithelial keratinization cycle. "The miR‐516a‐5p overexpression in patients with erosive oral lichen planus may contribute to the imbalance of T helper 1/2 cell‐associated inflammatory cytokine expression in human oral mucosal fibroblasts by targeting MAPK11 mRNA, promoting their proliferative and migratory capacities." (PMID 41457473, 2025).
pertussis (1 paper, 2025). A contagious bacterial respiratory infection caused by Bordetella pertussis. "Furthermore, the downregulation of Tnf, Mapk11, C3, Il1a, and Il1b in the tuberculosis and pertussis pathways reduces macrophages' ability to opsonize bacteria, perform phagocytosis, and initiate inflammatory responses." (PMID 40206211, 2025).
rectal cancer (1 paper, 2022). A primary or metastatic malignant neoplasm that affects the rectum.
renal failure (1 paper, 2024). "Another study, based on the SOMAscan proteomics platform, screened three proteins (Delta-like 1, endothelial cell adhesion molecule, and mitogen-activated protein kinase 11) as candidate biomarkers for predicting the risk of DKD progression to renal failure." (PMID 38481996, 2024).
triple-negative breast carcinoma (1 paper, 2023). An invasive breast carcinoma which is negative for expression of estrogen receptor (ER), progesterone receptor (PR), and human epidermal growth factor receptor 2 (HER2). "MAPKAPK3, AKT3, CDK5, IGF1R, and MAPK11 are potential prognostic markers and therapeutic targets of curcumin in patients with triple-negative breast cancer." (PMID 37569854, 2023).
tuberculous pleurisy (1 paper, 2021). "A total of eight possible biomarkers of tuberculous pleurisy were screened (RPL17, UBA7, NDUFB8, UQCRFS1, JUNB, PSMC4, PHPT1, and MAPK11)." (PMID 34925441, 2021).
cancer (42 papers, 2012 to 2025). A tumor composed of atypical neoplastic, often pleomorphic cells that invade other tissues. "The p38-MAPK signaling, including p38β (MAPK11) and p38γ (MAPK12), is associated with the development and progression of several types of cancer." (PMID 34777208, 2021). "p38 mitogen-activated protein kinase (MAPK) signaling including p38α MAPK (MAPK14), p38β (MAPK11), p38γ (MAPK12) and p38δ (MAPK13) is associated with the development and progression of several types of cancer." (PMID 32894113, 2020). "After NMI knockdown, the expression levels of MAPK signaling pathway members, including Raf1, MAPK11, MAP3K14 and MAP3K2, which are associated with cancer invasion and metastasis, were obviously decreased HCC-LM3." (PMID 28077802, 2017). "This raises the intriguing hypothesis that MAPK11/14 activation in therapy-resistant cancers could contribute to metastatic dissemination by promoting ECM-bound α2β1 integrin internalisation." (PMID 39666682, 2024). "In addition, the downregulation of MAPK11 gene expression in specific female tissue cancers has been determined with in-silico studies." (PMID 35008796, 2021). "However, the specific role of p38β (MAPK11) in cancer is still elusive, and further investigation is needed." (PMID 33053909, 2020). "Additionally, MAPK11 facilitates the upregulation of lipid transport protein 2 (LCN2), a factor linked to increased tumour development, invasion, and metastasis, thereby contributing to cancer progression." (PMID 40070022, 2025). "Therefore, the different levels of methylation within the CpG islands of MAPK11 between normal and cancer data sets may influence the decrease in expression of MAPK11 seen in cancer tissues and warrants further investigation as a possible biomarker." (PMID 34174910, 2021). "Interestingly, p38β (MAPK11) activation has been associated with stress signalling, suggesting the intriguing hypothesis that ECM uptake might be induced by the stress response during cancer dissemination." (PMID 39666682, 2024). "RNA-seq analysis of the effects of 24 h exposure of QN-302 on MIA PaCa-2 cells have previously shown that the mRNA levels in the prominent cancer pathway quadruplex-containing genes such as GLI1, MAPK11 and BCL-2 were downregulated by 1–2 fold." (PMID 36985425, 2023). "Focusing on female tissue-specific cancers, we outline a trend where MAPK11 expression in normal tissue is higher than that of early-stage BRCA, CESC, UCEC, and UCS cancer data sets." (PMID 34174910, 2021). "Moreover, disruption of α2 integrin, MAP3K1, MAPK11, PPP2R1A, and NHE1-mediated ECM internalisation significantly impaired cancer cell migration and invasion in 2D and 3D culture systems." (PMID 39666682, 2024). "This enunciates that MAPK11 signalling is the main contributor to cancer cell survival in never smokers." (PMID 37686122, 2023). "Indeed, mi-INTs are enriched in cancer-relevant oncogenes such as BRAF, ERK2, MAPK11/P38beta, and JNK1." (PMID 34199764, 2021). "For these tumor types, five cancer drivers were targeted only by NPs at < 100 nM, including Adenylate Cyclase 1 (ADCY1), Matrix Metallopeptidase 2 (MMP2), Aryl Hydrocarbon Receptor (AHR), Cyclin Dependent Kinase 2 (CDK2), and Mitogen-Activated Protein Kinase 11 (MAP3K11)." (PMID 31214023, 2019). "Inhibition of p38 MAPK with a specific inhibitor SB202190 that targets both MAPK11 and MAPK14 resulted in decreased cell viability in all never smoker cancer cell lines to different degrees." (PMID 37686122, 2023).
tumor (39 papers, 2012 to 2025). "SFTPA1, FOXL1, and MAPK11 are tumor-characteristic molecular markers." (PMID 38495669, 2024). "MAPK11 is a gene that plays a vital part in tumour cell proliferation and migration." (PMID 37525479, 2023). "As with mNPH alone, decreases in ERK2 and MAPK11 expression, following mNPH+radiation could demonstrate a reduction in tumor cell survival signaling through the p38/MAPK pathway." (PMID 31795829, 2019). "Moreover, the downregulation of miR-516a-5p and upregulation of TRAF6 and MAPK11 were confirmed by qRT-PCR in HCC tumor samples (P < 0.05)." (PMID 31822654, 2019). "Overexpression of MAPK11 can reverse the tumor suppressing effect of LINC01220 on EC." (PMID 31123170, 2019). "Acts by inhibit TRAF6 e MAPK11 and the NF-κB and MAPK pathways reducing inflammation induced apoptosis of tumor cells." (PMID 41465470, 2025). "We revealed that circ_0001955, TRAF6 and MAPK11 levels were increased, while miR-516a-5p levels were decreased in HCC tumor tissues compared to adjacent normal tissues." (PMID 31822654, 2019). "Through GSE dataset analysis and in vitro experiments, another controlling network with circ_0001955/ miR-516a-5p/ TRAF6 and MAPK11 axis, it has also been reported that circ_0001955 can facilitate HCC tumor growth by sponging miR-516a-5p to boost TRAF6 and MAPK11 expression." (PMID 36769372, 2023). "It was also found that ERK pathway was enriched in tumor specimen after receiving chemotherapy, several ERK pathway component genes expression elevated in KEGG and REACTOME GSEA results, such as MAPK10, MAPK13, MAPK11 and MAPKAPK3." (PMID 29296238, 2017).
infection (15 papers, 2012 to 2024). The state of being infected such as from the introduction of a foreign agent such as serum, vaccine, antigenic substance or organism. "As expected, Mapk11 (encoding p38B, the major inducer of NO-linked apoptosis) was upregulated as well, 24 h and 48 h after infection." (PMID 22280251, 2012). "Several MAPK encoding genes, such as MAPK11, MAPK12, and MAPK13, were significantly up-regulated under HN10 infection and MAPK10 was significantly up-regulated under JDm10 infection." (PMID 35893682, 2022). "In contrast, NLRP12 has a detrimental role in infection with S. typhimurium through negative regulation of NF-κB and MAPK11." (PMID 27779193, 2016). "In particular, we validated CTNNB1 S552 and p38 (MAPK11-14) T180/Y182 phosphorylation as well as CTNNB1 and p38 protein abundance dynamics upon MPXV infection." (PMID 39117661, 2024). "Twenty-four hours after infection, strong upregulation was assayed in NOS2, Mapk11, CASP8 and Casp3 genes." (PMID 22280251, 2012). "Seven differentially expressed genes (DDX58, STAT1, MX1, IRAK1, MAPK11, RELA, and ICAM1) were randomly selected and quantified using qRT-PCR to validate the differential expression observed in A549 cells using RNA-Seq across varying infection time points." (PMID 38673764, 2024). "Seventy-two hours after infection, Casp3 and NOS2 remained upregulated (4.4-fold and 7.7-fold, respectively, p < 0.001), while Mapk11 was no longer upregulated." (PMID 22280251, 2012).
bacterial infection (4 papers, 2014 to 2026). "Taken together, TNF and Mapk11, which encode TNF-α and p38β respectively, are shared between both parasitic and bacterial infection pathways." (PMID 40206211, 2025).
prostate (1 paper, 2016). "Future research focusing on the MAPK11 isoform independently may develop this information and advance therapeutic regimes for treating osteolytic prostate metastases." (PMID 26913608, 2016).
MAPK11 also shares sentences with these, for which no sentence is quoted: rheumatoid arthritis (5 papers); chronic obstructive pulmonary disease (3); colon carcinoma (3); Huntington disease (3); inflammatory bowel disease (3); ischemia (3); lung carcinoma (3); Cachexia (2); Lewis lung carcinoma (2); pancreatic cancer (2); uterine carcinosarcoma (2); acne (1); acute myeloid leukemia (1); acute respiratory distress syndrome (1); Anorexia (1); Arthritis (1); autoimmune disease (1); bladder cancer (1); bone cancer (1); cardiac arrhythmia (1); cardiovascular disease (1); cervical cancer (1); chromophobe renal cell carcinoma (1); clear cell renal cell carcinoma (1); colitis (1); congestive heart failure (1); Diabetes (1); diabetic cardiomyopathy (1); epilepsy (1); Ewing sarcoma (1).
A further 31 diseases each share a sentence with MAPK11 in 1 paper.